THBS1 (thrombospondin 1)
Diseases named in the same sentence as THBS1 in open-access papers (continued):
Sharing a sentence is not in itself a finding about the gene and the disease.
osteosarcoma (11 papers, 2017 to 2025). A usually aggressive malignant bone-forming mesenchymal neoplasm, predominantly affecting adolescents and young adults. "The expression of PDGF-AA, endostatin, endothelin-1 and CD26 has been previously shown to be positively correlated with tumor progression in osteosarcoma and the upregulation of serpin E1 and thrombospondin-1 in OS cells has been correlated with an increased risk of lung metastasis." (PMID 31195680, 2019). "We also found that in the primary cells derived from 3 osteosarcoma patients, THBS1 was more highly expressed in sarcospheres relative to that in residual cells." (PMID 40083708, 2025). "Our results revealed that THBS1 promotes cytoskeleton remodeling and pulmonary metastasis in osteosarcoma, and FAK play a role in this process." (PMID 40083708, 2025). "A previous study highlights that osteosarcoma cells (MG-63) with elevated thrombospondin-1 (TSP-1) levels undergo apoptosis and exhibit inhibited angiogenesis via the endothelial CD36 receptor." (PMID 40075313, 2025). "The results of the tail vein injection groups indicated that the knockdown of THBS1 reduced pulmonary metastasis in osteosarcoma." (PMID 40083708, 2025). "Lentiviral transfection was employed to knockdown or overexpress THBS1 in the 143B and MG-63 osteosarcoma cell lines." (PMID 40083708, 2025). "Our results also demonstrated that ITGA1 and ITGA6, two subunits of integrin, play a role in mediating extracellular signals in cells and that THBS1 promotes the dedifferentiation and metastasis of osteosarcoma cells." (PMID 40083708, 2025). "To further clarify the ability of THBS1 to promote osteosarcoma metastasis, we first injected tumor cells through the tail vein to establish a nude mouse pulmonary metastasis model." (PMID 40083708, 2025). "We also plan to develop competitive binding peptides to disrupt the signaling pathway of THBS1, which promotes the dedifferentiation of osteosarcoma." (PMID 40083708, 2025). "Then, we performed IHC on 79 human osteosarcoma specimens and observed that patients with higher expression of THBS1 had a worse prognosis (log-rank P = 0.0018)." (PMID 40083708, 2025). "To determine the specific stage at which THBS1 primarily influences the dedifferentiation of osteosarcoma cells, we analyzed the expression levels of THBS1 and ITGAs in osteosarcoma cells across various dedifferentiation time points." (PMID 40083708, 2025). "The results of tail vein injection groups showed that overexpression of THBS1 promoted osteosarcoma metastasis and then increased the lung wights." (PMID 40083708, 2025). "Our results demonstrated that THBS1 and ITGAs are the key molecules in osteosarcoma cell dedifferentiation." (PMID 40083708, 2025). "By the way, CD117, IBSP (Stro-1), ID1, SOX9, CD24, CD44 and THBS-1 were also reported to affect osteosarcoma growth and stemness." (PMID 34828292, 2021). "In this section, we aimed to investigate whether THBS1 promotes osteosarcoma cell migration and invasion in ivtro." (PMID 40083708, 2025). "Next, we investigated the role of THBS1 in the dedifferentiation of primary osteosarcoma cell." (PMID 40083708, 2025). "Once we identify the structural region where the interaction occurs, short peptide drugs that competitively bind to this domain may block the function of THBS1 in promoting the dedifferentiation of osteosarcoma cells." (PMID 40083708, 2025). "In addition, similar to osteosarcoma cell lines, which was demonstrated by F-actin staining, the overexpression of THBS1 in primary osteosarcoma cells promoted cytoskeletal remodeling." (PMID 40083708, 2025). "However, the role of THBS1 in promoting osteosarcoma pulmonary metastasis could be reversed by ITGA1 or ITGA6 knockdown." (PMID 40083708, 2025).
osteosarcoma (continued). "Further experiments revealed that RBMX regulates the expression of H2-K1 and THBS1, driving the depletion of CD8+T cells in osteosarcoma through cell communication." (PMID 40941025, 2025). "Our research has identified the key molecule THBS1, along with its downstream targets ITGA1 and ITGA6, which play a role in the dedifferentiation of osteosarcoma cells." (PMID 40083708, 2025). "Co-IP experiments confirmed the interaction between THBS1 and ITGA1/ITGA6 in the dedifferentiation of osteosarcoma cells." (PMID 40083708, 2025). "Thrombospondin 1 (THBS1) and ITGAs were identified as the key molecules in dedifferentiation through mRNA-seq and analysis, and osteosarcoma patients with higher THBS1 expression had a worse prognosis than those with lower THBS1 expression." (PMID 40083708, 2025). "Genes involved in epithelial cell proliferation, such as BCL11B, NRAS, THBS1, and VEGFC, promote angiogenesis and tumorigenesis, reflecting the heterogeneity of osteosarcoma-related genes." (PMID 35610231, 2022). "RNA-seq studies demonstrated that YAP as well as YAP-regulated genes, such as Cyr61, THBS1, PAI-1 and BIRC5, are significantly overexpressed in tissues derived from osteosarcoma patients as compared to normal bone tissues." (PMID 34440844, 2021). "Additionally, THBS1 enhanced the expression of p-MLC2, Stro-1, and CD117 in vivo, indicating its role in facilitating cytoskeleton remodeling and the dedifferentiation of osteosarcoma cells." (PMID 40083708, 2025). "In addition, during the sphere formation of osteosarcoma cells, the signal intensity of ITGA1 and ITGA6 on the cell membrane surface at the outer edge of the sphere was higher than that inside the sphere, and colocalization with THBS1 also occurred in cells at the outer edge of the sphere." (PMID 40083708, 2025).
endothelial dysfunction (10 papers, 2017 to 2025). In vascular diseases, endothelial dysfunction is a systemic pathological state of the endothelium (the inner lining of blood vessels) and can be broadly defined as an imbalance between vasodilating and vasoconstricting substances produced by (or acting on) the endothelium. "Previous studies have shown that THBS1 is associated with endothelial dysfunction by inducing the onset of inflammatory responses, and is involved in platelet aggregation and adhesion to endothelial cells." (PMID 36675257, 2023). "The present study conjectures the causal role of one such molecule THBS1 provoked under hypoxia and involved in the endothelial dysfunction, angiogenesis, and platelet aggregations incriminated in hypertension pathophysiology." (PMID 34575042, 2021). "Hence, THBS1 invariably associates with endothelial dysfunction by inducing the onset of inflammatory reactions and is involved in the process of platelet aggregation and adhesion to endothelial cells." (PMID 34575042, 2021). "The association of THBS1 with endothelial dysfunction implies its important role in hypertension." (PMID 34575042, 2021). "THBS1 promotes vascular inflammation by activating inflammatory pathways in the endothelium, leading to endothelial dysfunction." (PMID 40127075, 2025). "Thrombospondin-1 (TSP-1) is a glycoprotein known to inhibit nitric oxide signaling, contributing to endothelial dysfunction and immunological activation following transplantation." (PMID 40699682, 2025). "Recent studies suggested that, although found to function in the activation of MAPK/p38, thrombospondin-1, together with TNF-α, played critical roles in micro-endothelial dysfunction, such as increasing apoptosis and limiting angiogenesis." (PMID 29152123, 2017). "In fact, the present results revealed that MSC-CM did not contain TNF-α, which somewhat weakened the effects of thrombospondin-1 on endothelial dysfunction." (PMID 29152123, 2017).
ischemic stroke (10 papers, 2019 to 2023). A stroke disorder caused by obstruction of blood flow to the brain, due to thrombotic (local blood clot formation) or embolic (due to a blood clot or other material traveling from another site) event. "Association analyses of THBS1 variants with the incidence risk of ischemic stroke in the cohort study." (PMID 36212039, 2022). "The biological connection of genetic variants and mRNA expression of THBS1 with ischemic stroke (IS) warrants further validation with population-based evidence." (PMID 36212039, 2022). "Association analyses of THBS1 variants and the risk of ischemic stroke in the case-control study." (PMID 36212039, 2022). "THBS1 regulates angiogenesis and elevations in plasma levels have been reported in patients with ischemic stroke." (PMID 34926573, 2021). "Our data also showed that the expression of THBS-1 was higher in ischemic stroke patients than in healthy controls." (PMID 32466277, 2020). "We also confirmed that thrombospondin-1 and vitronectin are expressed on circulating endogenous EVs in human ischemic stroke." (PMID 31676801, 2019). "Cerebral THBS1 expression is upregulated in experimental focal cerebral ischemia and the circulating THBS1 were elevated in patients with ischemic stroke." (PMID 31262327, 2019). "Here, we show that astrocyte-derived thrombospondin-1 may impede axon regeneration in the glial scar after ischaemic stroke." (PMID 36072905, 2022). "Taken together, these results suggest that THBS-1 could serve as a blood biomarker for diagnosing ischemic stroke." (PMID 32466277, 2020). "In a previous study, THBS-1 showed higher expression in platelets of ischemic stroke patients than in platelets of healthy controls, suggesting that THBS-1 may serve as a suitable parameter for monitoring platelet activation." (PMID 32466277, 2020). "Interestingly, most of the top 10 upregulated DEGs, such as Thbs1, CD36, ITGA4, and ADAMTS12, are involved in the function of endothelial cells, as shown in the heatmap, implying a role of NeuroD1 in regulating the gene expression of endothelial cells post ischemic stroke." (PMID 38270116, 2023).
leukemia (10 papers, 2008 to 2024). A malignant (clonal) hematologic disorder, involving hematopoietic stem cells and characterized by the presence of primitive or atypical myeloid or lymphoid cells in the bone marrow and the blood. "LYN-defective fibroblasts acquire leukemia-suppressive properties, mediated—at least in part—by a remodeled matrix and the increased expression of THBS1, which induces CLL cell death." (PMID 36899005, 2023). "Some other downregulated genes are related to chemo-resistant or leukemia aggressiveness such as Thbs1, Tgm2, Ambp, and the AF9 regulator Sgk1, which negatively regulates the DOT1A-AF9 repressor complex." (PMID 28974232, 2017). "In contrast, transcript levels of some genes that are related with leukemia prognosis/aggressiveness, such as Ambp and Thbs1, were drastically repressed." (PMID 28974232, 2017). "The significantly lower level of THBS1 in CLL-LN fibroblastic cells suggests that suppression of leukemia-inhibitory factors in the stroma may represent a mechanism to promote tumor progression." (PMID 36899005, 2023). "THBS1 induces apoptosis of leukemia cells and could be a potential therapeutic target for AML patients." (PMID 33299888, 2020). "Taken together, all these results suggested that methylation of THBS1 gene in leukemia cell might be attributed to the low THBS1 levels of bone marrow serum." (PMID 32117788, 2019). "However, THBS1, which also indicated potential upregulation in the present study, was down regulated in leukemia and upregulated in lymphoma." (PMID 23343470, 2013). "Interestingly, increased levels of the CLL-restrictive matrix protein THBS1 were detected in the transcriptome and secretome of LYNKO HS-5 cells, potentially explaining this leukemia-restrictive ECM in LYNKO BMSC." (PMID 36899005, 2023).
lymph node metastasis (10 papers, 2010 to 2024). "Furthermore, high THBS1 expression was independently associated with recurrence, lymph node metastasis positivity, undifferentiated pathology, and microsatellite stable (MSS) status in the multivariate analyses." (PMID 37749092, 2023). "Worthy, in CAFs the expression levels of thrombospondin-1 along with other ECM components are correlated with an increased odd ratio for lymph node metastasis." (PMID 38937754, 2024). "Lower THBS1 expression is related to advanced grade of liver and lymph node metastases, coupled with worse overall survival." (PMID 31847842, 2019). "THBS1 and THBS2 were enriched in the patients of the S2 subgroup, who were characterized by higher lymph node metastasis and lower overall survival." (PMID 38339060, 2024).
pulmonary hypertension (10 papers, 2010 to 2023). Increased pressure within the pulmonary circulation due to lung or heart disorder. "A similar study demonstrated hypoxia-associated upregulation of THBS1 in the lungs due to increased HIF-2α protein expression in the pulmonary vasculature contributing to pulmonary arterial hypertension-driven vascular remodeling and vasoconstriction." (PMID 34575042, 2021). "THBS1 is highly expressed in the plasma and pulmonary vessels of patients with pulmonary hypertension." (PMID 36611783, 2023). "Regarding THBS1, this anti-angiogenic molecule seems to be involved in the pathophysiology of hypoxia-induced pulmonary hypertension and right ventricular hypertrophy." (PMID 34552509, 2021). "We found that DMF treatment reduced angiostatic thrombospondin-1 (TSP1) transcript levels in healthy control (HC) and pulmonary hypertension (PH) HPASMCs under normoxic and hypoxic conditions." (PMID 28150703, 2017).
type 2 diabetes (10 papers, 2017 to 2025). "Additionally, in type 2 diabetes, urinary exosomes showed significant up-regulation of miR-320c that increase TGF-β signaling by targeting thrombospondin-1 (TSP-1), which causes renal fibrosis and correlates with microalbuminuria." (PMID 40340661, 2025). "In conclusion, we show that fhFABP1 modulates T cell polarization, notably by promoting thrombospondin-1 secretion by dendritic cells in vitro, but does not affect metabolic homeostasis in a mouse model of type 2 diabetes." (PMID 35720355, 2022).
Hypertension (9 papers, 2014 to 2024). The presence of chronic increased pressure in the systemic arterial system. "Genotype-interactions between THBS1 rs2228263 and CD47 rs9879947 were relevant and the regression analysis highlighted the association of risk genotype-interactions with increased THBS1 levels in hypertension." (PMID 34575042, 2021). "Furthermore, the visceral THBS1 mRNA expression was positively associated with abdominal obesity, hyperglycemia, and hypertension." (PMID 36212039, 2022). "Interestingly, the gene–gene interaction model highlighted the risk contribution of THBS1 rs2228263TT/CT genotypes towards hypertension, which is also associated with the increased THBS1 levels." (PMID 34575042, 2021). "Finally, a study on the associations between genetic variants of Thrombospondin-1 Levels and high-altitude hypertension found significant associations between CD93 polymorphisms and arterial hypertension in a study sub-group of 349 people living at high altitude (>3500 mt)." (PMID 37371490, 2023). "Our findings indicated the important role of THBS1 levels in patients with hypertension." (PMID 34575042, 2021). "All of these functions of THBS1 imply its important role in hypertension pathophysiology." (PMID 34575042, 2021).
non-small cell lung carcinoma (9 papers, 2015 to 2025). A group of at least three distinct histological types of lung cancer, including non-small cell squamous cell carcinoma, adenocarcinoma, and large cell carcinoma. "Circular RNA (circRNA) THBS1 has been shown to exist as an oncogene in non-small-cell lung cancer, but its role in cervical cancer is still unclear." (PMID 37465349, 2023). "circRNA THBS1, a newly discovered circRNA, has been confirmed to regulate non-small-cell lung cancer cells’ functions by sponging miR-129-5p and regulating SOX4 expression." (PMID 37465349, 2023). "A study has shown that circRNA THBS1 promotes the migration and invasion of non-small-cell lung cancer cells by adsorbing the expression of miR-129-5p regulating gene SOX4." (PMID 37465349, 2023).
oral cancer (9 papers, 2017 to 2025). "Through network pharmacology studies, additional gene targets of quercetin for treating nicotine‐related oral carcinoma, such as THBS1, IGF1R, and SERPINE1, were identified." (PMID 41368332, 2025). "Oral cancer-derived exosomal thrombospondin 1 (THBS-1) activates M1-like macrophages through p38/Akt/SAPK/JNK signaling, enhancing cancer progression." (PMID 39200273, 2024). "THBS1 serves as a critical role in the angiogenesis of cancer cells and thus promotes the metastasis of oral cancer cells." (PMID 36033831, 2022). "Both heteronemin and tetrac inhibit THBS-1 expression in oral cancer cells." (PMID 35705962, 2022). "However, NDAT suppressed THBS1 expression in oral cancers in which THBS1 was shown to be involved in carcinogenesis." (PMID 34359854, 2021). "THBS-1 has been shown to play a tumorigenic role in oral cancers." (PMID 32630719, 2020). "In conclusion, our findings demonstrated that exosomal transfer of THBS1 from oral cancer could polarize macrophages into M1-like TAMs." (PMID 29986759, 2018). "Hence, it suggests that SMAD3, MMP3, SERPINE1, and THBS1 serve as tumor promoters in oral cancer." (PMID 36033831, 2022). "In vitro experiments demonstrated that quercetin can inhibit the expression of the core targets (THBS1, SERPINE1, and IGF1R), thereby suppressing the proliferation and metastasis of both nicotine‐transformed cells and oral cancer cells." (PMID 41368332, 2025). "Molecular docking and molecular dynamics simulations revealed that quercetin binds tightly to the core targets (THBS1, SERPINE1, and IGF1R) of nicotine‐related oral carcinoma, suggesting its potential as a therapeutic agent for oral cancer." (PMID 41368332, 2025). "A total of 29 genes shared by quercetin and nicotine‐related oral carcinoma were screened, and SERPINE1, IGF1R, and THBS1 were identified as hub genes." (PMID 41368332, 2025).
renal fibrosis (9 papers, 2019 to 2025). A final common manifestation of a wide variety of chronic kidney diseases characterized by glomerulosclerosis and tubulointerstitial fibrosis. "Based on previous studies, we determined that injury caused by crystal deposition is frequently accompanied by renal fibrosis and that THBS1, ITGA11, and SOCS2 can affect the fibrotic process." (PMID 34997271, 2022). "Our findings taken together have highlighted the multifaceted roles of platelets and THBS1, and their interplay in IR‐induced kidney injury, suggesting that targeting this pathway may be a potential therapeutic strategy to address renal fibrosis." (PMID 38838052, 2024). "Indeed, miR-320c downregulates the TGF-β signaling via targeting thrombospondin 1 (TSP-1) that is a key activator of TGF-β in renal fibrosis and shows an elevated expression in the glomeruli of DN patients." (PMID 35073973, 2022). "Among the differentially expressed proteins, THBS1 and CFHR5 emerged as potential markers of renal fibrosis and complement-mediated glomerular injury, while IGFBP3 reflected growth factor dysregulation associated with both renal and cardiac remodeling." (PMID 41301692, 2025). "Moreover, THBS-1 promoted renal fibrosis mainly by regulating the expression and activity of TGF-β in unilateral ureteral obstruction (UUO), a well-known model of renal fibrosis." (PMID 38258908, 2024).